CASP9 (caspase 9)
Diseases named in the same sentence as CASP9 in open-access papers (continued):
Sharing a sentence is not in itself a finding about the gene and the disease.
breast carcinoma (continued). "In summary, our study demonstrates that DUSP16 targets JNK and p38 to regulate the common cell death pathway, the BAX/caspase 3–caspase 9 pathway, in various types of solid tumors, including NPC, CRC, gastric cancer, and breast cancer to regulate chemotherapy-induced apoptosis." (PMID 33863904, 2021). "Specifically, we found that in MCF7 breast cancer cells, iodoacetate mediates apoptosis by upregulating BAX/BAK gene expression which in turn induced caspase 9 and p21 activation leading to increased cytotoxicity as confirmed by flow cytometry multiple measures." (PMID 31551501, 2019). "Overall, these data emphasized that epoxyazadiradione induces apoptosis through mitochondria-mediated caspase 9 and 3 activation but not through ROS-dependent manner in breast cancer cells." (PMID 29310608, 2018). "This can be presumed that TH could be a viable option to mediate hematological parameter, and expression of Caspase-9, Apaf-1, E2, Bcl-xL and ESR1 against breast cancer." (PMID 28399853, 2017). "In addition, our gene expression study showed PE-mediated upregulation of Bad, caspase-3, caspase-7, caspase-9, poly (ADP ribose) polymerase and cytochrome c in mammary tumors." (PMID 26699876, 2016). "The authors have described G2/M arrest, activation of caspase-9 and caspase-3/7 (but not caspase-8) in the metastatic breast cancer cell line MDA-MB-231 by boldine, which also down-regulates Bcl-2 and heat shock protein 70 and up-regulates Bax." (PMID 25719742, 2015). "We found that initiator caspase-9 was processed at very low levels after resveratrol treatment whereas caspase 3 was not immunodetected in MCF-7 breast cancer cells in agreement with previous studies." (PMID 23724044, 2013). "Our data demonstrated that CTHRC1, negatively regulated by miR-30c, promoted cell proliferation, invasion and migration and suppressed cell apoptosis in breast cancer, which might be by activating GSK-3β/β-catenin signaling and inhibiting Bax/Caspase-9/Caspase-3 signaling respectively." (PMID 28697793, 2017). "Thus, given these changes in expression AKt, Caspase 9 and Bax, we presume that the initiation of the observed apoptosis by the engineered MNPs may occur via the PI3K/AKT pathway that is known as the main pathway involved in breast cancer." (PMID 25880772, 2015). "Despite the low p-value, the two genes (CASP9 and FGF14-AS2) do not show prognostic power for breast cancer." (PMID 31856825, 2019). "Caspase-9 activities followed the similar pattern as caspase-3 and increased 5–6 folds at 16 h only in CHX-treated MCF-10A and HMLE cells, while no significant increased activity was detected in breast cancer cells." (PMID 21730980, 2011).
lung carcinoma (110 papers, 2006 to 2025). "The CASP3 rs4647601 TT genotype has also been linked to head and neck squamous cell carcinoma risk, while CASP9 rs4645981C is related to lung cancer incidence." (PMID 40344485, 2025). "The overexpression of Mcl-1L in PRKCSH-deficient cells suppressed TRAIL-mediated cell death and caspase-9 activation, whereas Mcl-1 depletion in lung cancer cells enhanced TRAIL-mediated cell death and caspase-9 activation." (PMID 38200153, 2024). "Our analyses showed a significant enrichment of genes encoding for known apoptosis mediators, such as FAS and CASP9 genes in human A549-rtTA-OSKM cells or Bid in mouse L1475luc-rtTA-OSKM lung cancer cells." (PMID 39587064, 2024). "An analysis of CASP9 promoter polymorphisms contributing to genetic susceptibility to lung cancer suggested that CASP9 polymorphisms and their haplotypes interacted with tobacco smoking." (PMID 27723786, 2016). "Further, in ebractenoid F-treated A549 and H460 human lung cancer cells, the expression levels of cancer growth- and migration-associated proteins decreased, as well as those of cell death-associated proteins (Bax, cleaved caspase-3 and cleaved caspase-9)." (PMID 36615523, 2022). "Knocking down Xb130 with siRNA in thyroid or lung cancer cells reduced cell survival, increased susceptibilities of cells to extrinsic and intrinsic signal-induced cell death, which was associated with increased cleavage of caspase-8 and caspase-9." (PMID 27029000, 2016). "Another member of the caspase family, caspase-9, has also been shown to be associated with the induction of apoptosis in several cancer cells including cervical cancer cells, human hepatoma cells, melanoma cells, and human lung cancer cells." (PMID 22363243, 2011). "Ionising radiation and luteolin combination therapy increased programmed cell death in lung cancer cells by downregulating Bcl-2, which in turn stimulated caspase-9, -8, and -3." (PMID 40427522, 2025). "Another study reported that autophagy blockade by HCQ significantly increased apoptosis in lung cancer cells by activating both the extrinsic (FOXO3a/FasL/caspase-8) and intrinsic (caspase-9) apoptotic pathways." (PMID 41303490, 2025). "In lung cancer (A549) cells, apigenin increases cytochrome C levels, which in turn inhibits mitochondrial function, thereby leading to Caspase-9 and Caspase-3 activation and subsequent apoptosis." (PMID 40490812, 2025). "BEAP inhibits the proliferation of lung-cancer-cell-line A549 by inducing apoptosis through increasing the Bax/Bcl-2 ratio, promoting the release of cytochrome C and activating caspase-3 and caspase-9." (PMID 40507156, 2025). "Our qRT-PCR results indicated that Odo A treatment led to upregulation of CASP3, CASP7, CASP8, and CASP9 expression, which suggests that the extrinsic route was responsible for blocking the development of lung cancer cells." (PMID 40141789, 2025). "Blocking ICAM-1–FGG interaction disrupts the survival signaling and activates caspase-9/3, thus inducing cancer cell apoptosis and prevents lung cancer progression in vivo." (PMID 39168965, 2024). "Piperine was reported to induce cell cycle arrest in the A549 lung cancer cell line at a concentration of 50, 100, and 200 μg/mL by upregulating caspase-3 and caspase-9 cascades and the Bax/Bcl-2 ratio." (PMID 37568796, 2023). "The results indicated that the genes FADD, TNFRSF1A, CASP9, MLKL, and CASP4 were the risk factor for lung cancer patients (p < 0.05)." (PMID 36874021, 2023). "p-Coumaric acid was reported to increase apoptosis in A549, NCI-H1299, and HCC827 lung cancer cell lines at a concentration of 10–100 μg/mL by upregulating caspase-3 and caspase-9." (PMID 37568796, 2023). "Again, FA4 was the only TSC to activate both caspase 7 and caspase 9 in breast and lung cancer cell lines." (PMID 37796435, 2023).
lung carcinoma (continued). "More specifically, indole-3-carbinol increased oxidative stress and expression of caspase-3, caspase-7, and caspase-9 to ultimately induce apoptosis in H1299 lung cancer cells at a concentration of 400 μM." (PMID 37568796, 2023). "Few data are available for the potential role of caspase-9 in malignancies, although increased expression of caspase-9 has been reported in lung cancer progressing to a metastatic phenotype and in colorectal cancer patients with a poor prognosis." (PMID 37730576, 2023). "When 5, 10, or 20 μM of honokiol was applied to A549 and 95-D lung cancer cell lines, researchers observed inhibited cell proliferation and migration, which they attributed to resultant increases in Bax, caspase-9, and PERK phosphorylation." (PMID 37568796, 2023). "Myrcene with a concentration of 1 μg/mL showed strong cell cycle arrest at G0/G1 phase and significantly increased the expression level of caspase-3, caspase-9, and cytochrome C in A549 lung cancer cells." (PMID 36556421, 2022). "HSP treated in H522 lung cancer cells mediated apoptosis with initiating Fas death receptor/extrinsic pathway, resulting in upregulating Bax, caspase-3, and caspase-9 in a dose-dependent manner." (PMID 35128104, 2022). "All caspase inhibitors reduced the MMP (ΔΨm) level in control Calu-6 cells, particularly the caspase-9 inhibitor, which significantly decreased the level in both lung cancer cell types." (PMID 35889456, 2022). "In the present study, the anti-apoptotic effects of various pan-caspase, caspase-3, caspase-8, and caspase-9 inhibitors were investigated in PG-treated Calu-6 and A549 lung cancer cells in relation to changes in ROS and GSH levels." (PMID 35889456, 2022). "The CerK inhibitor NVP-231 blocks the M phase of the cell cycle and activates the caspase-9/caspase-3 pathway to promote apoptosis in lung cancer cells, while the overexpression of CerK promotes cell proliferation and protects lung cancer cells from apoptosis." (PMID 35799611, 2022). "The down-regulated Bcl-2 associating with apoptosis induction which was indicated by chromatin condensation and/or nuclei fragmentation and activation of caspase-9 were presented in lung cancer cells after culture with 25 μM norcycloartocarpin for 24 h." (PMID 34383763, 2021). "The up-regulated ratio of cleaved caspase-9/caspase-9 correlated well with apoptosis cell death found in norcycloartocarpin-treated lung cancer cells." (PMID 34383763, 2021). "Regarding lung cancer, the chemopreventive role of FX was demonstrated in a mouse model of benzo(A)pyrene-induced lung cancer through apoptosis induction by enhanced caspase 9 and 3 levels and reduced expression of Bcl2 protein." (PMID 34677429, 2021). "We also showed that ANTP-SMACN7 promoted cell apoptosis through the inhibition of XIAP and activation of caspase-3 and caspase-9 in lung cancer cells after irradiation with high-LET IR." (PMID 34546667, 2021). "The results showed that ANTP-SMACN7 significantly promoted cell apoptosis through the inhibition of XIAP and the activation of caspase-3 and caspase-9 in lung cancer cells after irradiation with high-LET IR." (PMID 34546667, 2021). "In the H1650 lung cancer cell line, the pro-apoptotic Caspase-9, Bak, Puma, and Bax protein levels were elevated, while the anti-apoptotic Bcl-2 levels decreased significantly at unchanged Mcl-1 levels, after methyl-donor treatment." (PMID 33808426, 2021). "In lung cancer, PRRX1 knockdown inhibits the expression of Caspase 3, caspase 9, Apaf-1, and cytochrome C, leading to enhanced anti-apoptotic capacity and resistance to cisplatin in lung cancer cells." (PMID 32811812, 2020).
lung carcinoma (continued). "Bufalin decreases NCI-H460 cell activity in lung cancer and blocks tumor cells in the G0/G1 and G2/M phases, promoting apoptosis by increasing the production of oxygen-free radicals, caspase-1, and caspase-9." (PMID 32148531, 2020). "Disruption of MMP promotes the release of cytochrome C from the mitochondria into the cytoplasm, stimulates the activation of caspase-9 and caspase-3, and finally, leads to apoptosis of lung cancer cells." (PMID 31205586, 2019). "In the IL-32γ-overexpressing lung cancer cells, the percent of apoptotic cells was increased and the expression levels of pro-apoptotic proteins Bax, cleaved caspase-3 and caspase-9 were increased." (PMID 29467412, 2018). "TIPE2 has been demonstrated to promote the apoptosis by regulating caspase-9 and caspase-3 in both lung cancer and gastric cancer." (PMID 30534358, 2018). "Our results showed that the combination of FZKA treatment with STAT3 knock-down increased the activities of both caspase-3 and caspase-9 in lung cancer cells, compared to FZKA alone." (PMID 30046347, 2018). "TRIM9 and ZBTB38 are other E3 ligases where knockdown of these resulted in caspase-9 and 7 activations in human lung carcinoma and C2C12 cells, respectively." (PMID 29479529, 2018). "TRIM9 E3 ligase knockdown in human lung cancer tissues and cell lines reduces Bcl-2 expression while it activates the caspase-7 and caspase-9." (PMID 29479529, 2018). "Treatment with tumor necrosis factor-alpha (TNF-α) enhanced apoptosis in SAHA-treated lung cancer cells through caspase-8 and caspase-9 activations." (PMID 28099148, 2017). "By pretreating the cells with a specific inhibitor of caspase 9, the caspase-9-independent nature of the montelukast-induced cell death of lung cancer cells was confirmed." (PMID 28672809, 2017). "A similar regulation was found for Casp-9 in lung cancer cells in which activated AKT phosphorylates SRSF1, thereby inhibiting synthesis of anti-apoptotic Casp-9b isoform." (PMID 29286307, 2017). "Similar splicing modulation was found for caspase-9 (Casp-9) in lung cancer cells, in which activated AKT phosphorylated SRSF1, thereby leading to exclusion of an exon 3,4,5,6 cassette and generation of the anti-apoptotic Casp-9b isoform." (PMID 29286307, 2017). "Using caspase-9 inhibitor in the current study, the participation of caspase 9 was excluded from montelukast-induced lung cancer cell death." (PMID 28672809, 2017). "ECAP induces death in A549 lung cancer cells through the intrinsic-mitochondrial pathway by activating caspase-9." (PMID 26134408, 2015). "ECAP induces apoptosis in cultured lung cancer cells by activating the caspase intrinsic mitochondrial-mediated apoptosis pathway; activated caspase-9 will activate the executioner caspases-3/7 and result in down-stream cleavage of proteins such as PARP." (PMID 26134408, 2015). "RNAi-mediated knockdown of CLPTM1L increased chemosensitivity to cisplatin in human lung cancer 95-D cells and cisplatin-induced activation of caspase-9 and caspase-3/7." (PMID 23300716, 2012). "In summary, our results showed that RBM5 significantly inhibits tumor growth and induces apoptosis of lung cancer cells by reducing the expression of Bcl-2, subsequently inducing the expression of cleaved caspase-3, cleaved caspase-9 and cleaved PARP." (PMID 22866867, 2012). "Next, we examined the processing of caspase-9 in two representative lung cancer cell lines, H460 (NSCLC) and GLC4 (SCLC), after treatment for 24 and 48 h with IC80 concentrations of cisplatin." (PMID 16796750, 2006). "This previous report also showed much more appreciable activation of caspase-9 in lung cancer cells after treatment with γ-irradiation than with the cytotoxic drug etoposide." (PMID 16796750, 2006).
lung carcinoma (continued). "Further studies are required to unravel the role of TUCAN in tumor biology as well as to elucidate the molecular basis of caspase-9 inhibition in lung cancer cells." (PMID 16796750, 2006). "In conclusion, studies have shown that α-MMC mainly inhibits the expression of Bcl-2 through the mitochondrial pathway to activate the Caspase cascade, and significantly induces apoptosis of lung cancer cells through activation of effector protein caspase-3 and induction protein caspase-9." (PMID 40552155, 2025). "In lung cancer A549 cells, plumbagin could engender apoptosis via caspase-9 activation and ROS production." (PMID 37047251, 2023). "Therefore, the activation of caspase-3, caspase-8, and caspase-9 together appears to be necessary for the complete induction of apoptosis in PG-treated lung cancer cells." (PMID 35889456, 2022). "When lung cancer cells were treated with ATO/VPA, cleaved forms of caspase-8 and caspase-9 were increased, implying that caspase-8 linked with the cell death receptor (extrinsic) pathway was activated in these cells, and caspase-9 related to the mitochondrial (intrinsic) pathway was also activated." (PMID 32290325, 2020). "The pretreatment with MitoTEMPO significantly reduced the BA6-induced cytotoxicity, ROS overproduction, and MMP disruption and finally inhibited the caspase-9 and caspase-3 activation and reduced apoptosis (early and late apoptosis) induction in lung cancer cells." (PMID 31205586, 2019). "Finally, the expression of apoptotic genes caspase 9 and caspase 3 involving in intrinsic apoptosis pathway during the treatment of A549 lung cancer cells were examined." (PMID 29491463, 2018). "Our results showed that FZKA induced the cleavage of caspase-9 and caspase-3 in lung cancer cells." (PMID 30046347, 2018). "The combination of PDT and curcumin in lung carcinoma cells and in laryngeal squamous cell carcinoma cells induced an upregulation of caspase-9 and caspase-3, suggesting that the intrinsic pathway (caspase 9) is involved in the curcumin-PDT-induced death of tumor cells." (PMID 29581972, 2018). "In the present study Dox@PVP-AuNPs complex enhances the expression of caspase 9 and caspase 3 and AO/EB staining assay confirmed the apoptosis in lung cancer by emitting red color fluorescence in Dox@PVP-AuNPs chromatin condensation and formation of apoptotic bodies by bright blue fluorescence." (PMID 29491463, 2018). "Thus ECAP depolarized the mitochondrial membranes of A549 lung cancer cells resulting in cytochrome c release and the subsequent activation of caspase-9." (PMID 26134408, 2015). "In present study, we provide evidences firstly indicate that TIPE2 suppresses the growth and promotes apoptosis of lung cancer through regulating the Bcl-2/Bax balance and then leads to the activation of caspase-3 and caspase-9 possibly via affecting P38 and Akt pathway." (PMID 25946186, 2015). "RPS has been found to up-regulate the expression of pro-apoptotic proteins, such as active caspase-3, active caspase-9, and Bax in nonsmall cell lung cancer cells, hepatoma xenografts, ovarian cancer cells, and Hela cells, indicating that RPS induce apoptosis by mitochondrial apoptotic pathway." (PMID 26147856, 2015). "Another steroidal saponin, polyphyllin D from Paris polyphylla, was tested on human lung cancer NCI-H460 cells and caused upregulation of endoplasmic reticulum (ER) stress-related proteins, disruption of mitochondrial membrane, and activation of caspase-9 and -3." (PMID 36500274, 2022).